FTH1P3 (ferritin heavy chain 1 pseudogene 3)
Synonyms: formerly FTHL3
Gene: Processed pseudogene on chromosome 2 (27,392,784 to 27,393,367, reverse strand). Ensembl gene ENSG00000213453.
Diseases named in the same sentence as FTH1P3 in open-access papers:
FTH1P3 is named in the same sentence as 19 diseases in open-access papers, as found by Europe PMC text mining. Sharing a sentence is not in itself a finding about the gene and the disease. The quoted sentences say what the papers report.
uveal melanoma (8 papers, 2018 to 2021). A melanoma derived from melanocytes of the uveal tract. "In addition, it was indicated that the upregulation of FTH1P3 targeted miR-224-5p in uveal melanoma, and caused an increase in the expression of RAC1 and Fizzled 5, which are direct target genes of miR-224-5p." (PMID 34771549, 2021). "FTH1P3 can promote cell proliferation, migration, invasion, and tumor progression in uveal melanoma, oral squamous cell carcinoma, laryngeal squamous cell carcinoma, cervical cancer, and NSCLC." (PMID 34771549, 2021). "For example, FTH1P3 facilitated progression of glioma, uveal melanoma, and oral squamous cell carcinoma." (PMID 32185172, 2020). "LncRNA FTH1P3 is up-regulated in several human cancers, including uveal melanoma, oral squamous cell carcinoma, esophageal squamous cell carcinoma, glioma, breast cancer, cervical cancer, and non-small cell lung carcinoma." (PMID 33260500, 2020). "FTH1P3 expression was also increased in uveal melanoma and elevated expression of FTH1P3 promoted cell proliferation, cell cycle and migration of uveal melanoma." (PMID 32185172, 2020). "Previous literature has found that FTH1P3 promoted cell proliferation and invasion in uveal melanoma." (PMID 31142627, 2019). "FTH1P3 expression was inversely correlated with the miR-224-5p expression in uveal melanoma tissues." (PMID 31179240, 2019). "Similarly, in 25 uveal melanoma patient samples, a higher expression of FTH1P3 was observed than in the 25 normal samples (p < 0.01)." (PMID 34771549, 2021). "As a result, FTH1P3 has a critical role in uveal melanoma progression, and could be a potential therapeutic target for uveal melanoma." (PMID 34771549, 2021). "FTH1P3 also plays an oncogenic role in uveal melanoma cells." (PMID 30071685, 2018). "Previous literatures have reported that FTH1P3 is up-regulated in oral squamous cell carcinoma (OSCC) and uveal melanoma." (PMID 31142627, 2019). "Further studies have found that FTH1P3 facilitates cell growth and invasion through regulating microRNA-224-5p in OSCC and uveal melanoma." (PMID 31142627, 2019). "Previous documents have found that FTH1P3 is up-regulated in OSCC and uveal melanoma, and promotes tumor progression." (PMID 31142627, 2019).
breast carcinoma (5 papers, 2018 to 2026). "Taken together, results revealed that lncRNA FTH1P3 was up‐regulated in paclitaxel‐resistant breast cancer tissue and cells, suggesting the underlying molecular role in breast cancer chemoresistance." (PMID 29971911, 2018). "In a xenograft mouse model, silencing FTH1P3 was found to suppress the growth of paclitaxel-resistant breast cancer cells and decrease the expression of the ABCB1 protein." (PMID 41362671, 2026). "For example, in breast cancer cells, the lncRNA FTH1P3 promotes P-gp expression and activates paclitaxel resistance by acting as a molecular sponge of miR-206." (PMID 31920517, 2019). "Then, lncRNA FTH1P3 was increased in paclitaxel‐resistant breast cancer cell lines (MCF‐7/PTX, MDA‐MB‐231/PTX) compared to their parental cell lines (MCF‐7, MDA‐MB‐231)." (PMID 29971911, 2018). "In summary, results indicated that FTH1P3 silencing suppressed the tumour growth of paclitaxel‐resistant breast cancer cells and ABCB1 protein in vivo." (PMID 29971911, 2018). "In vivo, xenograft mice assay showed that FTH1P3 silencing suppressed the tumour growth of paclitaxel‐resistant breast cancer cells and ABCB1 protein expression." (PMID 29971911, 2018). "Results showed that lncRNA FTH1P3 was up‐regulated in paclitaxel‐resistant breast cancer tissue compared with that in paclitaxel‐sensitive samples." (PMID 29971911, 2018). "Previous results had indicated that lncRNA FTH1P3 was up‐regulated in paclitaxel‐resistant breast cancer tissue and cells." (PMID 29971911, 2018). "In conclusion, above evidence reveals the vital role of lncRNA FTH1P3 in the paclitaxel resistance of breast cancer." (PMID 29971911, 2018). "Taken together, our results illuminate the FTH1P3/miR‐206/ABCB1 pathway in the chemoresistance of breast cancer." (PMID 29971911, 2018). "Overall, all the data concluded that lncRNA FTH1P3 activated the paclitaxel sensitivity and induced the G2/M phase arrest of breast cancer cells in vitro." (PMID 29971911, 2018). "Results showed that lncRNA FTH1P3 was up‐regulated in paclitaxel‐resistant breast cancer tissue and cells (MCF‐7/PTX and MDA‐MB‐231/PTX cells) compared with paclitaxel‐sensitive tissue and parental cell lines (MCF‐7, MDA‐MB‐231)." (PMID 29971911, 2018). "In this study, we investigate the physiopathologic role of lncRNA ferritin heavy chain 1 pseudogene 3 (FTH1P3) on the paclitaxel (PTX) resistance in breast cancer." (PMID 29971911, 2018). "It had been verified that lncRNA FTH1P3 was up‐regulated in paclitaxel‐resistant breast cancer cells and FTH1P3 regulated the paclitaxel sensitivity of breast cancer cells in vitro." (PMID 29971911, 2018). "Our team performed bioinformatics predictive tools to investigate the potential regulatory pathway of FTH1P3 in the paclitaxel‐resistant breast cancer cells." (PMID 29971911, 2018). "Interestingly, the lncRNA ferritin heavy chain 1 pseudogene 3 (FTH1P3) was found to be elevated in breast cancer tissues and cells that are resistant to paclitaxel, in comparison to paclitaxel-sensitive tissues and parental cell lines." (PMID 41362671, 2026). "The potential regulatory mechanism by which the FTH1P3 influences paclitaxel resistance in breast cancer, through its involvement with the miR-206/ABCB1 pathway, provides a new view that could lead to advancements in breast cancer chemotherapy." (PMID 41362671, 2026). "Because FTH1P3 and ABCB1 are both up‐regulated in paclitaxel‐resistant breast cancer cells, we could conclude that miR‐206 targets simultaneously with FTH1P3 and ABCB1." (PMID 29971911, 2018). "Therefore, we could conclude that the abnormal overexpression of FTH1P3 participate in the chemotherapy resistance, promoting the paclitaxel resistance in breast cancer tumorigenesis." (PMID 29971911, 2018). "FTH1P3 promotes the paclitaxel resistance in human breast cancer tumorigenesis by targeting miR‐206/ABCB1 axis, suggesting the novel molecular mechanism of breast cancer chemotherapy resistance." (PMID 29971911, 2018).
oral squamous cell carcinoma (5 papers, 2017 to 2020). "Moreover, it was shown that FTH1P3 promotes the proliferation, migration, and invasion of oral squamous cell carcinoma by the association with Wnt/β-catenin via PI3K/Akt/GSK-3b signaling." (PMID 33260500, 2020). "FTH1P3 (ferritin heavy chain 1 pseudogene 3) has been shown to function as a molecular sponge for miR-224-5p in oral squamous cell carcinoma (OSCC)." (PMID 29147648, 2017). "In the last few years, FTH1P3 has been identified in a group of up-regulated lncRNAs in oral squamous cell carcinoma (OSCC) and has been shown to function as an oncogenic regulator to facilitate OSCC progression by regulation of the miR-224-5p-Frizzled 5 pathway." (PMID 33260500, 2020).
glioma (4 papers, 2019 to 2021). A benign or malignant brain and spinal cord tumor that arises from glial cells (astrocytes, oligodendrocytes, ependymal cells). "Overexpression of FTH1P3 enhanced glioma cell proliferation and inhibited apoptosis by regulating miR-224-5p/TPD52 pathway." (PMID 32185172, 2020). "It has been proven that the FTH1P3/miR-224-5p/TPD52 axis is responsible for glioma progression." (PMID 34947885, 2021). "Overexpression of FTH1P3 promotes glioma cell proliferation and inhibits apoptosis." (PMID 34947885, 2021).
colorectal cancer (2 papers, 2024 to 2025). A primary or metastatic malignant neoplasm that affects the colon or rectum. "In colorectal cancer, miR-218-5p repressed the expression of FTH1P3, a gene responsible for inducing cell migration and EMT." (PMID 40805149, 2025). "The lncRNA ferritin heavy chain 1 pseudogene 3 (FTH1P3) has been reported to promote tumor progression in colorectal cancer, cervical cancer, and NSCLC." (PMID 38540273, 2024).
laryngeal squamous cell carcinoma (2 papers, 2019 to 2024). A squamous cell carcinoma that arises from the larynx. "And increased E2F1 expression via the E2F1/FTH1P3/miR-377-3p/LDHA axis promoted cell viability and glycolysis in laryngeal squamous cell carcinoma." (PMID 39546499, 2024).
lymph node metastasis (2 papers, 2019 to 2021). "High FTH1P3 expression was positively correlated with poor differentiation, high T classification, positive lymph node metastasis, and advanced clinical stage." (PMID 31142627, 2019). "We determined whether the expression level of FTH1P3 was correlated with the clinicopathological features of LSCC patients, including gender, age, primary location, T classification, differentiation, lymph node metastasis, and clinical stage." (PMID 31142627, 2019).
oral cancer (1 paper, 2021). "Moreover, the FTH1P3 transcript was associated with advanced tumor stage and poor prognosis in oral cancer." (PMID 34440428, 2021). "FTH1P3 pseudogene transcript was also associated with oral cancer risk and prognosis by becoming a miRNA sponge for miR-224-5p and thereby modulating the expression of the FZD5 (frizzled class receptor 5) gene, facilitating cell proliferation and colony formation." (PMID 34440428, 2021).
tumor (9 papers, 2017 to 2024). "In addition, the FTH1P3 pseudogene transcript was associated with advanced tumor stage and worst overall survival in laryngeal cancer by enhancing cell proliferation, migration, and invasion, and inhibiting cell apoptosis, although the exact mechanism was not elucidated." (PMID 34440428, 2021). "For example, the targeting of FTH1P3 lncRNA by shRNA suppressed the tumor growth of paclitaxel-resistant BC cells in a xenograft mice assay." (PMID 37958880, 2023). "A study in vivo showed that the silencing of FTH1P3 suppressed the tumor growth of paclitaxel-resistant BC cells and ABCB1 protein expression in a xenograft mice assay." (PMID 37958880, 2023). "Pseudogene-derived lncRNAs such as PHBP1, PTTG3P, and FTH1P3 function as tumor promoters or tumor suppressors in ESCC." (PMID 34016787, 2021). "Knockdown of FTH1P3 decreases the 50% inhibitory concentration value of paclitaxel, induces cell cycle arrest at the G2/M phase, and suppresses tumor growth of paclitaxel-resistant BC cells as well as ABCB1 protein expression in vivo." (PMID 34947885, 2021). "Results showed that FTH1P3 knockdown significantly decreased the tumour volume compared to empty vector group." (PMID 29971911, 2018). "Then, xenograft mice assay in vivo was performed using MCF‐7/PTX cells to test the role of FTH1P3 on tumour growth." (PMID 29971911, 2018). "FTH1P3 could promote proliferation, migration, and invasion of tumor cells, possibly by PI3K/Akt/GSK3β/Wnt/β-catenin signaling." (PMID 34440428, 2021). "Besides, FTH1P3 knockdown significantly down‐regulated tumour weight compared to empty vector group." (PMID 29971911, 2018). "Additionally, knockdown of FTH1P3 represses the tumor growth in vivo." (PMID 34947885, 2021). "In the tumour tissue sample, Western blot showed that ABCB1 protein was decreased in FTH1P3 knockdown group compared to empty vector group." (PMID 29971911, 2018).
cancer (5 papers, 2017 to 2023). A tumor composed of atypical neoplastic, often pleomorphic cells that invade other tissues. "FTH1P3 is a newly identified lncRNA in cancer cells, and its overexpression in cancer cell lines and tissues has been demonstrated by several studies." (PMID 34771549, 2021). "In addition, miR‐206 targets the 3′‐UTR of mRNA encoding ABCB1, thus, upregulation of FTH1P3 and ABCB1 in paclitaxel‐resistant cancer cells derived from TBNC suggested FTH1P3 targets miR‐206, thereby freeing ABCB1 expression." (PMID 37795578, 2023). "Seven (PA2G4P4, ATP5EP2, FTH1P3, ANXA2P3, ANXA2P1, HNRNPA1P33, and HSP90B3P) of the 14 pseudogenes that our analysis revealed as important for pan-cancer classification were previously found to be differentially expressed in various cancers." (PMID 28673244, 2017).
FTH1P3 also shares sentences with these, for which no sentence is quoted: non-small cell lung carcinoma (3 papers); esophageal squamous cell carcinoma (2); cervical cancer (1); colon carcinoma (1); endometrial cancer (1); melanoma (1); myelogenous leukemia (1); osteoarthritis (1); osteosarcoma (1).